LINC00421 (long independently transcribed non-coding RNA 421)
Gene: Long non-coding RNA gene on chromosome 13 (19,344,466 to 19,346,810, forward strand). Ensembl gene ENSG00000236834.
Diseases named in the same sentence as LINC00421 in open-access papers:
LINC00421 is named in the same sentence as 1 disease in open-access papers, as found by Europe PMC text mining. Sharing a sentence is not in itself a finding about the gene and the disease. The quoted sentences say what the papers report.
osteoporosis (1 paper, 2021). A condition of reduced bone mass, with decreased cortical thickness and a decrease in the number and size of the trabeculae of cancellous bone (but normal chemical composition), resulting in increased fracture incidence. "The ANKRD26P3 gene (near LINC00421 gene) at the 13q12.11 position was associated with post-menopausal osteoporosis and large artery atherosclerosis (LAA)." (PMID 34067580, 2021).